CD59 (CD59 molecule (CD59 blood group))
Diseases named in the same sentence as CD59 in open-access papers (continued):
Sharing a sentence is not in itself a finding about the gene and the disease.
rheumatic disease (1 paper, 2020). "CD55 and/or CD59 erythrocytes are present in a majority of patients with rheumatic disease." (PMID 33362763, 2020).
schizophrenia (1 paper, 2020). A major psychotic disorder characterized by abnormalities in the perception or expression of reality. "In contrast, CD59 mRNA was increased by 20.8% in schizophrenia cases compared to controls (F = 10.89, df = 53,1, p = 0.002)." (PMID 33133060, 2020). "Conversely, CD59, which inhibits the formation of the membrane attack complex and cell lysis and can also be considered a “don't eat me” signal, is increased in the high inflammatory schizophrenia cases." (PMID 33133060, 2020). "The particularly strong positive correlation between CD59 and CD163 transcripts in the schizophrenia cases indicates that macrophages are most likely protected from complement-induced damage." (PMID 33133060, 2020). "CD163 mRNA was strongly positively correlated with CD59 mRNA in schizophrenia cases (r = 0.52, p = 0.007) but not in controls (r = −0.008, p = 0.97) and the z transformation test was significantly different (z = −2.05, p = 0.04)." (PMID 33133060, 2020).
sickle cell disease (1 paper, 2020). Sickle cell anemias are chronic hemolytic diseases that may induce three types of acute accidents: severe anemia, severe bacterial infections, and ischemic vasoocclusive accidents (VOA) caused by sickle-shaped red blood cells obstructing small blood vessels and capillaries. "Like in the before mentioned anemias, differential expression of CD55 and CD59 on erythrocytes was also found in sickle cell disease patients." (PMID 33362763, 2020). "Although these patients expressed decreased CD55 and CD59 expression on RBCs, this could not be linked to disease severity, suggesting that these regulators do not play a significant role in the pathophysiology of hemolysis in sickle cell disease." (PMID 33362763, 2020).
synovial sarcoma (1 paper, 2015). "Poorly differentiated variant of synovial sarcoma can be diagnosed on the basis of expression of CD56 and CD59." (PMID 26101678, 2015).
teratoma (1 paper, 2024). A non-seminomatous germ cell tumor characterized by the presence of various tissues which correspond to the different germinal layers (endoderm, mesoderm, and ectoderm). "Transplantation of these cells that also expressed covalent single chain trimers of Qa1 and H2-Kb to inhibit NK cells and CD55, Crry, and CD59 to inhibit complement deposition led to persistent teratomas in wild-type mice." (PMID 38215755, 2024).
uterine cancer (1 paper, 2025). Primary or metastatic malignant neoplasm involving the uterine corpus and/or the cervix. "Similarly, increased CD55 and CD59 expression was observed on cell membranes and in the TME of ovarian and uterine cancers." (PMID 40370471, 2025).
vivax malaria (1 paper, 2019). "Further, the level of CD55 and CD59 on reticulocytes was positively associated with haemoglobin level for falciparum and vivax malaria, respectively (CD55: R = 0.53, p = 0.053; CD59: R = 0.55, p = 0.027)." (PMID 31533836, 2019). "Expression of CR1, CD55, CD59, and CD47 was also assessed on reticulocytes during falciparum and vivax malaria and healthy controls." (PMID 31533836, 2019). "CD59 expression on uninfected normocytes was reduced in mildly-anaemic compared to non-anaemic vivax malaria patients (p=0.017)." (PMID 31533836, 2019).
tumor (121 papers, 1993 to 2026). "CD59 is a membrane complement regulatory protein, which is highly expressed in many reproductive system tumors and is related to tumor immune deficiency." (PMID 35387305, 2022). "Four proteins (FSCN1, SIPA1, SPTBN1 or CD59) closely associated with tumor metastasis interacted with FASN and exhibited decreased expression in response to FASN silencing." (PMID 32699531, 2020). "siRNA mediated downregulation of CD59 sensitized the HBx-positive tumor cells and rendered them susceptible to CDC, suggesting new therapeutic avenues in HBV–HCC patients." (PMID 33718121, 2020). "High expression of the mCRPs membrane cofactor protein (CD46), decay-accelerating factor (CD55), and CD59 (protectin) on tumor cells is associated with increased metastatic potential, and poor prognosis in a range of tumors." (PMID 31001273, 2019). "The expression of CD59 in the tumor tissue was significantly associated with the histological grade (p = 0.034)." (PMID 31685825, 2019). "The univariate analysis showed that a worse overall patient survival was significantly associated with high CD59 expression in the tumor tissues (p = 0.025), the N stage (p = 0.018) and the histological grade (p = 0.010)." (PMID 31685825, 2019). "Because of the great deal of data showing that CD46, CD55, and CD59 expression are linked to worse clinical outcomes, and are in some cases highly specific for tumor cells, many approaches to block mCRP expression on tumor cells have been studied." (PMID 31164885, 2019). "The CD59-sufficient or -deficient Eca109 cells were implanted into Balb/c nude mice, which were treated with a single dose of 20 Gy γ-rays on day 13 when the tumor volume reached 0.3 – 0.5 cm3." (PMID 30166523, 2018). "Moreover, unfavorable outcomes were strongly associated with the expression of CD59 and M2 tumor-associated macrophage infiltration in the TME via the IL10/pSTAT3 pathway in CESC and GBM but not in KIRC." (PMID 39518137, 2024). "Recently, increasing research has demonstrated that CD59 is highly expressed in various forms of malignant tumor, including breast, prostate and gastrointestinal cancer, suggesting that CD59 is closely associated with tumor progression." (PMID 32699531, 2020). "Moreover, a great deal of data showed that mCRP expression, contains CD46, CD55, and CD59, are linked to worse clinical outcomes, and in some cases highly specific for tumor cells, many approaches to block mCRP expression on tumor cells have been studied." (PMID 33614473, 2020). "In addition, KLF4 is a stem cell marker that promotes cancer stem cell population maintenance and CD59 upregulation may be associated with tumor cell immune escape." (PMID 22900095, 2012). "Sponges miR-216b and miR-150 to upregulate CD55 and CD59 expression and suppress complement system activation to promote tumor immune evasion." (PMID 41409273, 2025). "Utilizing combined therapies of antibodies targeting both CD55/CD59 and programmed death 1 (PD-1) results in a collaborative effect that inhibits tumor growth." (PMID 40515636, 2025). "CD59 prevents the formation of membrane attack complex, enabling tumor cells to escape complement-mediated cytotoxicity." (PMID 39518137, 2024). "Further, the correlation between CD59 and Treg and/or MDSC in the tumor microenvironment (TME) has shown to be strongly associated with poor outcomes in CESC, GBM, HNSC, and STAD as these tumors express high FOXP3 compared to KIRC." (PMID 39518137, 2024). "UMAP visualization showed that CD59 was expressed in various types of cells including tumor cells in human localized, metastatic HSPC, and CRPC tumor tissues." (PMID 39436703, 2024). "Our correlation analysis of CD59 emphasizes the importance of understanding its interactions with other immune components across different tumor models, as these dynamics can affect outcomes." (PMID 39518137, 2024). "In most cancers, CD59 acts as a defense mechanism utilized by tumor cells to evade destruction by the immune system." (PMID 39518137, 2024).
tumor (continued). "Recent studies have shown that CD59 is highly expressed in several cancer cell lines and tumor tissues." (PMID 37006234, 2023). "CD59 also regulates the function, infiltration and phenotypes of a variety of immune cells in the tumor microenvironment." (PMID 37006234, 2023). "Critically, NANOG+ tumor cells enriched through selective pressure imposed by CTLs preferentially expressed CD59 via transcriptional regulation, thereby promoting the CDC-refractory phenotype." (PMID 35606403, 2022). "In this process, NANOG upregulated the membrane-bound complement regulatory protein (mCRP) CD59 through promoter occupancy, thereby contributing to the resistance of tumor cells against complement-dependent cytotoxicity (CDC)." (PMID 35606403, 2022). "Mechanism of the anti-tumor effect of ICT-CMC-CD59sp microspheres: The overexpression of CD59 suppresses the formation of the membrane attack complex (MAC), by which tumor cells can avoid recognition by the complement pathway." (PMID 35387305, 2022). "In this respect, we observed increased expression levels of mCRPs, such as CD46, CD55, and CD59, in P3 tumor cells over the course of CTL-mediated immune editing." (PMID 35606403, 2022). "Recent studies have indicated that CD59 is highly expressed in several cancer cell lines and tumor tissues, including those from CRC patients." (PMID 36612172, 2022). "In keeping with the other models, treatment of EMT6 tumor-bearing mice with G9668 for 7 d significantly increased surface levels of MHC-I and CD59 in tumor-infiltrating cDC1s." (PMID 35446348, 2022). "We also demonstrate that tumor C1q expression is positively associated with survival outcome in HER2+ BC patients and that complement regulators CD55 and CD59 were inversely correlated with outcome, suggesting the clinical importance of complement activity." (PMID 35167491, 2022). "Tumor cells themselves can express variable degrees of CD59 to evade destruction by complement, and the resistance to CDC can even be much higher than that of normal cells." (PMID 35725455, 2022). "The expression levels of CD59 were also detected with IHC assay in another set of tumor tissues from 147 DLBCL patients, which were followed up for 5 to 57 months." (PMID 34956875, 2021). "The augmented expression of CD55 and CD59 suggested a predominant role in progression of ccRCC, whereas the amount of CD46 was significantly associated to tumour stage." (PMID 34572075, 2021). "The presence of anti-CD59 on the NP surface conferred tumor selective accumulation properties, as CD59 has been shown to be overexpressed in cancer and associated with immune escape events." (PMID 34073766, 2021). "CD59 has been found to be overexpressed in tumor cells as well as in immune cells involved in the microenvironment of the tumor." (PMID 33374813, 2020). "For example, siRNA-mediated downregulation of CD46, CD55 and/or CD59 on several primary tumors and tumor cell lines sensitizes them to CDC." (PMID 33147799, 2020). "CD59 has been reported to mediate proliferation, adhesion and migration of tumor cells through various signaling pathways." (PMID 32699531, 2020). "Upregulation of CD59 expression enables tumor cells or tumor stem cells to avoid recognition by the complement pathways." (PMID 32337233, 2020). "Our data indicate that PTX3 might play a significant pathogenic role in the development of this neoplasia through recruitment of the early components of Complement cascade with hampered activation of terminal Complement pathway associated with the upregulation of CD59." (PMID 33110136, 2020). "In fact, CD59 is overexpressed by most tumors and very effectively protects tumor cells from complement attack." (PMID 32337233, 2020). "Cancer cells can be protected from CDC by high expression of CD59, and the function of immune cells in the tumor microenvironment can also be affected by CD598." (PMID 31685825, 2019).
tumor (continued). "Overexpression of CD59 can increase the expression of anti-apoptotic protein Bcl-2 and promote tumor cell growth and proliferation." (PMID 31413735, 2019). "This has shown to be due to the influence of membrane-bound complement regulatory proteins such as CD46, CD55, and CD59 which are overexpressed in tumour cells." (PMID 31544882, 2018). "We observed that the CD59-deficient tumors were significantly more sensitive to irradiation than the CD59-sufficient tumors, demonstrated by tumor growth, tumor images, and tumor weight at the endpoint of the experiment." (PMID 30166523, 2018). "A significant inverse correlation was observed between miR-10a-5p and CD59 expression, implying a biologically relevant, functional miRNA-mRNA target interaction, which would enhance tumor cell survival and thus render the tumor less sensitive to chemotherapy." (PMID 28400759, 2017). "On RNA level, we found an upregulation in 19.2% (five cases), although the general rate of CD59 transcript was significantly lower in tumor tissue (P = 0.03)”." (PMID 20805891, 2010). "Among the genes represented in the Met library, many are associated to tumor growth, invasiveness and metastasis, such as TM4SF1, LAMA4, G3BP2, CD59 antigen, and SPP1." (PMID 18211678, 2008). "The lack of MAC was probably due to the expression of C membrane regulators CD46, CD55 and CD59 on the tumour cells." (PMID 15726105, 2005). "In carcinomas CD59 expression in the whole neoplastic compartment was more often found in well- and moderately differentiated tumours." (PMID 7692919, 1993). "Noteworthy membrane-bound CRPs in tumors include CD46, CD55, and CD59, while soluble ones encompass factor I, factor H, and properdin.Although CD46, CD55, and CD59 are pivotal complement regulators expressed across most cell types and tumor cells, they exhibit a double-edged sword role." (PMID 40370471, 2025). "Upregulated by epidermal growth factor receptor (EGFR)/the wingless-related integration site (Wnt) signaling, LINC00973 functions as a ceRNA to sequester miR-216b and miR-150, leading to elevated expression of complement inhibitors CD55 and CD59 on tumor cells." (PMID 41409273, 2025). "Moreover, the combination of anti-CD55/CD59 and anti-PD-1 antibody treatments resulted in a synergistic tumor-suppressive effect." (PMID 40728857, 2025). "Taken together, this evidence indicates that high CD59 levels may play a key role in immune escape, leading to tumor development and poor prognosis." (PMID 39518137, 2024). "CD59 is expressed on the surface of tumor cells, potentially in order to limit CDC." (PMID 37371512, 2023). "The expression of inhibitory mCRPs like CD46, CD55 and CD59 can protect tumor cells from CDC." (PMID 36119088, 2022). "We found that the levels of CD59 were increased as the tumor progressed from normalcy to cancer." (PMID 35606403, 2022). "Among the mCRPs upregulated upon CTL-mediated immune selection, CD59 had dominant effects on the CDC-resistant phenotype; hence, we attempted to elucidate the underlying mechanism responsible for CD59 upregulation in CTL-resistant tumor cells." (PMID 35606403, 2022). "Nearly all human tumor cells, except NB cells, express CD59; thus, enhanced ADCC activity of H3‐16 IgG1m4 might be more important in GD2‐positive cancers other than NB." (PMID 35792784, 2022). "We found that, while this reduced dose of T+P could only moderately inhibit control KPL-4 tumor growth, knockdown of CD55 and CD59 in the same tumors resulted in profound tumor growth suppression." (PMID 35167491, 2022). "Our microspheres can bind specifically to the CD59 receptor of tumor cell CD59 led by CD59sp, guide drugs to reach the cell surface, activate complement to form MAC, and dissolve OSCC tumor cells, and then, through receptor-mediated endocytosis, the drug were taken to the cells’ interior." (PMID 35387305, 2022).
tumor (continued). "CD59 is highly expressed in several cancer cell lines and tumor tissues and regulates the function, infiltration, and phenotypes of various immune cells in the tumor microenvironment." (PMID 34917513, 2021). "CD59 overexpression in HNSCC was mediated by the tumor microenvironment, and may be a mechanism to escape from complement attack." (PMID 34069237, 2021). "We assessed tumor cell characteristics associated with immune suppression (PD-L1, CD47, and HVEM) or known tumor features associated with response/resistance to daratumumab treatment (expression levels of CD38 and the complement inhibitory proteins CD55 and CD59)." (PMID 34070044, 2021). "CD59's primary role is to regulate immune cell activation throughout the tumor microenvironment." (PMID 34803519, 2021). "In addition to the well-known function of CD59 to protect normal cells in the body against self-attack by MACCs, CD59 is involved in tumor growth." (PMID 33053147, 2020). "Similarly to these soluble regulators, the membrane-bound C inhibitors CD46, CD55 and CD59 are up-regulated in various primary tumors and tumor lines to evade the C attack." (PMID 33643290, 2020). "Similarly, the membrane-bound complement inhibitors (e.g. CD46, CD55, and CD59) are up-regulated in various primary tumors and tumor lines to evade the complement attack." (PMID 33193442, 2020). "FASN may bind to SPTBN1 and CD59 to mediate invasion and migration in tumor cells, and regulate the activation of the TGF-β-induced EMT." (PMID 32699531, 2020). "TAMs that infiltrated the tumor had a positive correlation with CD59 expression (R2 = 0.724)." (PMID 31685825, 2019). "Elements of the ComC may protect tumor cells from NK attack by membrane-bound or soluble regulators (e.g., CD55, CD59, and factor H) and by suppression of anti-tumor T cell immunity." (PMID 31231394, 2019). "Therapeutic strategies that regulate the function of CD59 in the tumor immune microenvironment may be a promising method for tumor immunotherapy." (PMID 31685825, 2019). "However, tumor cells maliciously hijack CD59 to escape from complement immune surveillance and complement-dependent cytotoxicity (CDC) induced by anticancer antibodies." (PMID 30166523, 2018). "We show a significant inverse correlation between miR-10a-5p and CD59 expression levels in eBL tumors, pointing to a potentially functional miRNA-mRNA relationship which could promote tumor cell survival, chemoresistance and poor outcomes." (PMID 28400759, 2017). "Importantly, knocking down of CD59 in tumour bearing mice led to a survival rate of 70% compared with 0% in the counterparts with undisrupted CD59 expression." (PMID 26891293, 2016). "MCP and CD59 were strongly expressed on all the tumour cells." (PMID 15726105, 2005). "Therefore, in this article, we have investigated the expression, prognostic significance, and impact on immune cell infiltration in the tumor microenvironment using CD59 expressive cancer patient data in The Cancer Genome Atlas (TCGA) and various publicly available databases." (PMID 39518137, 2024). "In light of this, our data propose that increase in CD59 might result from immune selection of NANOG+ CTL-refractory tumor cells, but it may not be its cause, at least during CTL-mediated immune selection." (PMID 35606403, 2022). "According to the classification of CD59 expression levels in tumor tissues, the number of TAMs that infiltrated the tumor tissues with a high level of CD59 expression was significantly higher than the number of TAMs in tissues with low CD59 expression (p < 0.001)." (PMID 31685825, 2019). "However, it is unclear how these cytokines regulate the expression of CD59 in tumor cells." (PMID 31413735, 2019).